KRAS (KRas proto-oncogene, GTPase)
Diseases named in the same sentence as KRAS in open-access papers (continued):
Sharing a sentence is not in itself a finding about the gene and the disease.
cancer (continued). "ARS-1620 (a potent, orally bioavailable covalent inhibitor of KRAS c.34G > T (p.G12C), when combined with alisertib (AURKA inhibitor), was observed to have a significant synergistic effect in ARS-1620-refractory KRAS c.34G > T (p.G12C) mutant cancer." (PMID 36077640, 2022). "It has been also indicated that a conformation-specific KRAS G12C inhibitor leads to a rapid non-uniform adaptation where some cancer cells stabilize its active drug-insensitive state and maintain cancer cells in a drug-resistant state." (PMID 36359850, 2022). "In accordance with pharmacologic KRAS inhibition, genetic Kras modulation did not impact the in vitro response of cancer cell lines to deltarasin, as determined by WST-8 IC50 values and ERK activation levels." (PMID 35327394, 2022). "In the PDAC Panc-1 human cell line and other cancer cells, ECM detachment induces autophagy, which in turn protects from detachment-induced cell death (anoikis) and facilitates glycolysis, promoting adhesion-independent transformation driven by oncogenic KRAS." (PMID 35159234, 2022). "In this study, we observed that ethanol conditioning increased proliferation, a hallmark of cancer, in HPNE cells harboring the G12D KRAS mutation, but not in HPNE with wild-type KRAS." (PMID 35454872, 2022). "Setting the hallmarks of cancer as the reference gene sets, GSEA demonstrated that hallmarks such as epithelial-mesenchymal transition and signaling pathways like NOTCH signaling, KRAS signaling, and TNFα signaling via NF-κB were significantly enriched in the low DLL3 expression group." (PMID 36338696, 2022). "In contrast, no members of the MMP were conserved in KRAS-mut and NEK cancers but several member genes were highly mutated." (PMID 36612014, 2022). "Remarkably, while enhanced MAPK1 activation associated with oncogenic mutations in upstream signal transducers (e.g., KRAS, HRAS, NRAS, and BRAF) is a common finding in cancer, MAPK1 mutations do not represent a major somatic event contributing to oncogenesis." (PMID 36394128, 2022). "KRAS, IL-SAT5, and the Hedgehog signaling pathway were screened out based on APOBEC3G’s high expression, all of which were closely related to the development of cancer cells." (PMID 36144542, 2022). "We hypothesize cancer cells with greater basal STAT3 activity will trap SBT-100 within the cytoplasm to a greater extent, thereby enhancing SBT-100′s ability to inhibit KRAS." (PMID 35886918, 2022). "Besides, activating signaling pathways like PI3K-AKT-mTOR pathway, JAK-STAT pathway and KRAS-ERK pathway, can regulate PD-L1 expression in many cancer types." (PMID 35346207, 2022). "In contrast to PDAC, KRAS mutations are usually not considered an initial driving event in CRC, instead being responsible for the progression of adenomas to malignant carcinomas." (PMID 36383067, 2022).
cancer (continued). "In a panel of cancer cell lines, MP-3995 inhibited proliferation in KRAS dependent lines but not in KRAS independent lines." (PMID 35024121, 2021). "The PH-domain inhibitor PHT-7.3 effectively prevents the colocalization of CNK1 with membrane-localized RAS and inhibits cell growth of KRAS-mutant cancer cell lines but not KRAS wild-type cell lines." (PMID 34208655, 2021). "Furthermore, it has been shown that in cancer cells with stem-like properties, RALB is recruited by the αvβ3 integrin to the plasma membrane together with KRAS and NF-κβ." (PMID 34359657, 2021). "In this study, cancer cell-restricted genetic ablation of mDR in autochthonous KRAS-driven models of non-small cell lung cancer (NSCLC) and PDAC was shown to reduce tumor growth, blunt metastasis, and prolong survival by inhibiting cancer cell-autonomous migration, proliferation, and invasion." (PMID 33810241, 2021). "Herein, our study reveals the impact of COL11A1 gene product in the alteration of PTEN, PIK3CA, KRAS, and BRAF which might downregulate the RTK-RAS-PI3K signaling pathways to induce cancer development." (PMID 33597969, 2021). "Previous studies have reported that regulation of TERT, KRAS, and CDKN2A could serve as potential therapeutic targets in multiple cancer types." (PMID 34442467, 2021). "Importantly, PLK1 is a synthetic lethal target in cancer driven by mutant KRAS, although how PLK1 crosstalks with oncogenic KRAS signaling remains incompletely understood." (PMID 34369083, 2021). "LMS1 was further characterized by several oncogenic signatures in the MAPK and MET signaling pathways (including KRAS and BRAF signatures), as well as cancer aggressiveness (cell migration, hypoxia) and a signature of resistance to the standard chemotherapeutic agent 5-fluorouracil." (PMID 34470666, 2021). "KRAS-dependent effector functions increase the expression of so-called immune checkpoints like programmed death ligand-1 (PDL1), which by binding to PD1 prevents T cells from killing cancer cells." (PMID 33809660, 2021). "For instance, in KRAS-dependent mutant cancer, dual knockout of RhoA/Rho kinase (ROCK) and polp-like kinase-1 by siRNA enhanced the expression of the cyclin-dependent kinase, which ultimately impaired the growth of KRAS-mutant cells’ proliferation." (PMID 34575504, 2021). "Studies to date have generally demonstrated limited efficacy of MEK1/2 selective inhibitors in RAS mutant cancers, and trametinib specifically did not demonstrate clinical efficacy in KRAS mutant PDAC." (PMID 34771675, 2021). "KRAS, NRAS proto-oncogene GTPase (NRAS), and HRas proto-oncogene GTPase (HRAS) are members of RAS proto-oncogenes family (RAS) and they play an important role in human cancers." (PMID 35048058, 2021). "The transcription of YAP1 and TAZ in the Hippo signaling pathway plays a critical role in mediating the resistance of major cancer treatment drugs, and is considered to play a major driving role in the development of resistance of BRAF- and KRAS- mutant cancer cells." (PMID 33996543, 2021).
cancer (continued). "Furthermore, inhibition of EML4-ALK with crizotinib in H3122 patient-derived cancer cells suppressed not only wild-type RAS-GTP levels, but also the levels of GTP-bound, cytosolic KRAS-C185S." (PMID 33848463, 2021). "KRAS is the most commonly mutated oncogene, yet no effective targeted therapies exist for KRAS-mutant cancers." (PMID 34373755, 2021). "The most obvious commonality here is that in addition to genetic factors (such as oncogenic KRAS) non-genetic factors such as stable reprogramming of cancer genomes contribute to human carcinogenesis." (PMID 33674596, 2021). "MEK inhibitors also caused feedback reactivation of ERK and have shown limited to no activity in KRAS mutant cancers." (PMID 34805167, 2021). "Several studies have suggested that a mutant KRAS protein may induce cyclin D1 overexpression through the constitutive activation of the RAS-MEK-ERK pathway, resulting in cell growth and cancer development." (PMID 33923563, 2021). "KRAS is commonly considered the worst of the three RAS GTPases for cancer promotion; our pan-cancer analysis rather suggests that the issue of which oncogenic RAS GTPase is most cancer-promoting may be dependent upon the type of cell in which cancer develops." (PMID 34645806, 2021). "All patients had undergone KRAS and NRAS assessment of their cancer." (PMID 34207352, 2021). "Furthermore, GSEA revealed that the malignant hallmarks of cancer, including Wnt/β-catenin signaling, HEME metabolism, UV response, KRAS signaling, bile acid metabolism, and MITOTIC spindle were closely associated with the high-risk subgroups." (PMID 35047491, 2021). "Unlike NSCLC driven by other less frequent oncogenic drivers (e.g., EGFR, ALK, MET1, and ROS1) that significantly benefit from selective kinase inhibitors, there are still no clinically approved therapies that specifically target KRAS‐mutant cancers." (PMID 34369083, 2021). "MiR-1205 serves as a cancer suppressor by disengaging the interplay of MDM4/E2F1 and KRAS in NSCLC." (PMID 33589572, 2021). "The co-occurrence of MET and KRAS or MET and PIK3CA might increase the aggressiveness of cancer cells, including cell proliferation, survival, invasion, or metastasis." (PMID 34439385, 2021). "Clinical trials utilizing TgTCR targeting KRAS G12V (NCT03190941) and G12D (NCT03745326) in the context of HLA-A*11:01 and utilizing up to five personalized TgTCR (NCT03412877) are currently being carried out across a wide range of cancer indications." (PMID 34439399, 2021). "Through analyses of these cells and of human oncogenic KRAS-, NRAS- and BRAF-driven cancer cell lines we identified that resistance to single MEK inhibitor and ERK inhibitor treatments arise rapidly but combination therapy completely blocks the emergence of resistance." (PMID 33924486, 2021). "Currently, several recombinant immunotoxins are undergoing clinical trials against different types of cancers, however, none is currently in the pipeline against KRAS-positive cancers." (PMID 33959410, 2021). "Anti-EGFR therapy including cetuximab and panitumumab significantly improves the survival of KRAS wild-type MSKCC, but not of those with KRAS-mutant cancer, suggesting that the single-drug therapy of cetuximab is insufficient to achieve a therapeutic effect." (PMID 34299137, 2021). "In addition, our network-based approach suggests that known oncogenic hub genes such as KRAS and MYC are prime targets for disruption in cancer cells." (PMID 34662337, 2021). "A mathematical model of a minimal network was developed, and computer simulations were carried out, which suggest that the positive feedback loops of both KRAS and mTOR pathways have crucial roles in determining the GLUT1 transport and autophagy induction upon cancer development." (PMID 33925206, 2021).
cancer (continued). "Taking these together, FAM83 members may regulate or be regulated by KRAS or SMAD4 in PDAC, leading to cancer progression." (PMID 33747255, 2021). "Thus, given the emerging oncogenic roles of YAP1 in cancer metabolism and KRAS mutant tumors, we also aimed to investigate the role of YAP1 in the regulation of AATs expression and function in KRAS mutant CRC cells." (PMID 34003553, 2021). "The dramatically reduced survival was observed in mutant KRas-driven cancer cells, while no significant growth inhibition was observed for the normal cells." (PMID 35069209, 2021). "Pharmacological and genetic suppression of FGFR1 and PLK1 synergizes to enhance anti‐proliferative effects and cell death in KRAS‐mutant lung and pancreatic but not colon nor KRAS wild‐type cancer cells." (PMID 34369083, 2021). "Furthermore, ADAM9 is upregulated by aberrant KRAS/NF-kB signaling in cancer cells, and knocking down ADAM9 suppresses KRAS and MEK-ERK signaling." (PMID 33648511, 2021). "We also detected that enhanced effects from AMG510 for cancer cell killing result from either IN10018 or YAP1 siRNA, further supporting that the aberrantly activated FAK–YAP signaling contributes to the compromised efficacy of KRAS G12C inhibitors." (PMID 34151545, 2021). "It is noteworthy that over 30 years following the discovery of the role of KRAS in cancer growth and development, no drugs targeting KRAS are currently in clinical trials." (PMID 33450835, 2021). "The regulatory complexity of PRC2+-CGI genes in cancer was also evident from the types of biological pathways we identified among these genes compared to other CGI genes, including important cancer-related pathways such as EMT, KRAS signalling, and TNFα signalling and inflammatory response." (PMID 33931649, 2021). "As far as we know, despite these promising properties, no molecule targeting the membrane localization of KRAS in cancer is currently in clinical trial." (PMID 34947990, 2021). "Several clinical vaccination trials testing vaccination against mutant KRAS have shown a survival benefit to patients who develop an immune response to the vaccination antigen, thus establishing the potential of TSA-specific therapeutic cancer vaccines." (PMID 33718228, 2021). "In addition to activating MAPK signaling, KRAS is also known to activate the PI3K-AKT-mTORC1 pathway, contributing to cancer progression." (PMID 34947990, 2021). "Genetic mutations have been shown to be hugely important in the study of many cancers and pancreatic cancer is no different, with GNAS and KRAS mutations representing the predominant mutations observed in this cancer." (PMID 33673153, 2021). "In 2020, the FDA granted an expanded access program for the ERK inhibitor ulixertinib (BVD-523) for the treatment of cancer patients with abnormal MAPK pathways, including but not limited to those involving KRAS, NRAS, HRAS, BRAF, MEK, and ERK mutations." (PMID 34607583, 2021). "Activation of RTK signaling in KRASG12C mutant cancers could limit the KRASG12C therapeutic inhibition both by increasing regulation of GTPase activity and promoting KRAS independent ERK and mTOR/S6 pathway activation." (PMID 33777798, 2021).
cancer (continued). "Each harbors overlapping yet distinct sets of co-clustering phosphosites—KRAS p.S89/p.Y96, NRAS p.Y64, and HRAS p.Y32/T35/Y64/Y96—warranting further investigation into their potentially shared and distinct signaling functions across cancer types." (PMID 33875650, 2021). "Even if KRAS could be effectively inhibited by new therapies, YAP amplification could provide a potential pathway for cancer recurrence." (PMID 33408779, 2021). "Decreased expression of RDM1 was noticed to be related to stimulated calcium signaling which contributed to cancer cell survival, together with activated KRAS and RAF pathways which, as upstream of MEK/ERK pathways, enhanced cancer cell growth, survival and metabolism." (PMID 34046411, 2021). "The KRAS/MAPK signaling pathway is strongly related to the growth and survival of cancer cells." (PMID 34512755, 2021). "Knockdown of PTPN2 reduced the proliferation and promoted apoptosis in KRAS-dependent cancer cells, but not in KRAS-independent cells." (PMID 33122197, 2020). "We next investigated the effect of PTPN2 on cancer cell growth, using pooled siRNAs to knockdown PTPN2 in a panel of five mutant KRAS-harboring human cancer cell lines (H460, PaTu8988T, HCT-116, A549, and DLD-1) and two KRAS wildtype human cancer cell lines (HT-1080 and SK-MEL-30)." (PMID 33122197, 2020). "To identify potential drugs that could reverse the KRAS-driven PDAC gene signature, we employed the CMap database that contains numerous gene signatures from cultured human cancer cell lines treated with drugs." (PMID 32947833, 2020). "Interestingly, YAP expression was critical for the progression of various KRAS-driven cancers, and YAP/KRAS converged on FOS to promote the EMT, which contributed to oncogenic KRAS oncogenic addiction." (PMID 32984007, 2020). "While important cancer drivers such as TGFB1 and KRAS exhibited wide intratumoral expression." (PMID 32642694, 2020). "Our findings suggest that therapeutic blockade of PI3K/Akt or mTORC1, but not KRAS, signalling in cancer can induce a switch in secreted exosome subtype, although in some cells, complete mTORC1 inhibition appears to strongly reduce all exosome secretion." (PMID 32720716, 2020). "In 17 of the 18 cases, at least one somatic mutation in the initiating driver genes KRAS and GNAS was shared between the noninvasive component and associated invasive cancer, with the remaining case lacking mutations in these genes." (PMID 32796935, 2020). "Since the initial work on KRAS, others have used PNA clamps for the purpose of cancer diagnostics." (PMID 32059456, 2020). "Because the therapy-resistant cancer cells, which commonly undergo EMT, are more sensitive to ferroptosis inducers, we next investigated the effect of co-treatment of β-elemene and cetuximab on cell migration of KRAS mutant CRC cells." (PMID 32308771, 2020). "It has been shown that proliferation and growth of a significant proportion of KRAS mutant cancer cell lines are not dependent on mutant KRAS." (PMID 32524209, 2020). "Other significantly enriched pathways (FDR q-value < 0.05) were “hypoxia”, “KRAS signaling”, “myogenesis”, “angiogenesis”, and “apical junction”, supporting the hypothesis that PXN is related to the metastatic ability of cancer cells." (PMID 33322675, 2020). "We therefore examined the total number of cancer-specific enhancer links in samples with and without KRAS or EGFR genetic alterations and in the highest quartile and remaining quartiles of expression of FOXM1 and MYBL2, respectively." (PMID 32925947, 2020). "The triterpenoid lupeol was reported to inhibit farnesyl transferase and, thus, to inhibit the growth of KRas mutant cancer cell lines but not of wild-type KRas-expressing cells." (PMID 33182807, 2020). "Furthermore, the list of typically early drivers includes most other highly recurrent cancer genes, such as KRAS, TERT and CDKN2A, indicating a preferred role in early and possibly even pre-cancer evolution." (PMID 32025013, 2020).